RBM46 (RNA binding motif protein 46)
Description:
Essential for male and female fertility, playing a crucial role in regulating germ cell development by ensuring the proper progression of meiosis prophase I (By similarity). Regulates mitotic- to-meiotic transition in spermatogenesis by forming a complex with MEIOC and YTHDC2 which recognizes and down-regulates mitotic transcripts for a successful meiotic entry (By similarity). Required for normal synaptonemal complex formation during meiosis, binding meiotic cohesin subunit mRNAs containing GCCUAU/GUUCGA motifs in their 3'UTRs regions and positively regulating their translation (By similarity). Required for spermatogonial differentiation in both developing and adult testis (By similarity).
Synonyms: CT68; MGC27016
Tractability: PROTAC: ubiquitination databases record sites on it; its protein half-life has been measured.
Gene: Protein-coding gene on chromosome 4 (154,781,213 to 154,828,813, forward strand). Ensembl gene ENSG00000151962.
Subcellular location: Cytoplasm
Subcellular location (Human Protein Atlas): Cytosol; Nucleoli fibrillar center
Gene Ontology:
Molecular function: protein binding; mRNA binding; enzyme-substrate adaptor activity; nucleic acid binding; RNA binding
Biological process: cell cycle switching, mitotic to meiotic cell cycle; female meiotic nuclear division; male meiotic nuclear division; oogenesis; spermatid differentiation; spermatogenesis; negative regulation of mRNA catabolic process
Cellular component: cytoplasm; nucleus; apolipoprotein B mRNA editing enzyme complex
Genetic constraint (gnomAD): Loss-of-function variants: 11 observed, 37.04 expected, observed/expected ratio (o/e) 0.3, 90% interval 0.19 to 0.49. The upper end of that interval is the gene's LOEUF score, 0.49, which puts it in group 2 of 6, group 1 being the genes least tolerant of losing a copy. Missense variants: 381 observed, 628.11 expected, observed/expected ratio (o/e) 0.61, 90% interval 0.56 to 0.66. Synonymous variants: 200 observed, 207.15 expected, observed/expected ratio (o/e) 0.97, 90% interval 0.86 to 1.09.
Homologues: Orthologues: dog RBM46 (98% identical), pig RBM46 (98% identical), rat Rbm46 (97% identical), mouse Rbm46 (96% identical), chimpanzee RBM46 (88% identical), macaque RBM46 (88% identical), rabbit RBM46 (87% identical), tropical clawed frog rbm46 (74% identical), zebrafish rbm46 (61% identical). Paralogues in human: A1CF (51% identical), RBM47 (48% identical), DND1 (21% identical), RBM19 (13% identical), HNRNPA2B1 (12% identical), NUCLEOLIN (12% identical), HNRNPA1 (12% identical), HNRNPA3 (12% identical), RBM39 (12% identical), TIA1 (12% identical), HNRNPA1L3 (12% identical), HNRNPA1L2 (12% identical), and 24 more.
Diseases named in the same sentence as RBM46 in open-access papers:
RBM46 is named in the same sentence as 2 diseases in open-access papers, as found by Europe PMC text mining. Sharing a sentence is not in itself a finding about the gene and the disease. The quoted sentences say what the papers report.
Infertility (3 papers, 2022 to 2023). "To test this hypothesis, we generated Rbm46 KO (Rbm46-/-) male mice and discovered loss of RBM46 blocked the completion of spermatogonia differentiation, preventing sperm formation and resulting in infertility." (PMID 36129965, 2022). "An infertility phenotype was reported for zebrafish lacking RBM46; RBM46 KO animals failed to initiate meiosis." (PMID 36726756, 2023). "Furthermore, the fact that male Rbm46-/- mice were otherwise normal, without any phenotypes other than infertility, is not compatible with an essential role of RBM46 outside of the germline." (PMID 36129965, 2022).
RBM46 also shares sentences with these, for which no sentence is quoted: cancer (1 paper).